MARCKS (myristoylated alanine rich protein kinase C substrate)
Diseases named in the same sentence as MARCKS in open-access papers (continued):
Sharing a sentence is not in itself a finding about the gene and the disease.
melanoma (continued). "Similarly, rWNT5A induced the accumulation of phosphorylated MARCKS in membrane protrusions at the leading edge of melanoma cells." (PMID 32033033, 2020). "MARCKS expression was reduced in A2058 melanoma cells by two different MARCKS siRNAs treatments." (PMID 32033033, 2020). "Interestingly, we observed that the Ser-159 and Ser-163 phosphorylation levels of MARCKS were significantly higher when compared to the Ser-167 and Ser-170 phosphorylation levels in all tested melanoma cell lines." (PMID 32033033, 2020). "Interestingly, stimulation with rWNT5A caused an increase in the numbers of invasive cells, whereas MARCKS silencing led to a 30–40% reduction in A2058 melanoma cell invasion compared to the control siRNA-transfected cells." (PMID 32033033, 2020). "Moreover, WNT5A-induced invasion of melanoma cells was blocked by siRNA targeting MARCKS, indicating a crucial role of MARCKS expression and/or its phosphorylation." (PMID 32033033, 2020). "Interestingly, WM852 melanoma cells which had higher WNT5A levels expressed significantly elevated amounts of MARCKS when compared to the other melanoma cell lines (HTB63, A375 and A2058 cells)." (PMID 32033033, 2020). "Therefore, it is very difficult to draw a solid conclusion with regard to how MARCKS expression relates to overall survival of melanoma patients." (PMID 32033033, 2020). "This prompted us to directly test whether RhoA-ROCK signaling is also involved in WNT5A-mediated phosphorylation of MARCKS in melanoma cells." (PMID 32033033, 2020). "However, the increase in MARCKS phosphorylation at Ser-159/163 was statistically significant after 15 minutes of rWNT5A treatment in both A2058 and A375 melanoma cell lines." (PMID 32033033, 2020). "A2058 melanoma cells expressing very low amounts of WNT5A but with significant expression of the MARCKS protein were used to test whether the WNT5A-induced melanoma cell invasion was dependent on the presence of the MARCKS protein." (PMID 32033033, 2020). "It has been found that phosphor-MARCKS is highly expressed in melanoma cells." (PMID 29757215, 2018). "The role of MARCKS in cell motility during melanoma progression is poorly understood." (PMID 27689402, 2016). "Notably Skmel28, which has the highest level of MARCKS, has a very elongated morphology on collagen, and is the melanoma line with the lowest level of microRNA-200c." (PMID 20957176, 2010). "Interestingly, we demonstrated that inhibition of PKC and ROCK signaling blocked WNT5A-mediated MARCKS phosphorylation and melanoma cell invasion, which indicated that both PKC and RhoA-ROCK, as intermediate signaling pathways, are crucial during WNT5A-regulated MARCKS function." (PMID 32033033, 2020). "Importantly, these results did not discriminate as to whether it was the expression or the phosphorylation status of MARCKS that is crucial for WNT5A-induced melanoma cell invasion." (PMID 32033033, 2020). "Since MARCKS is an actin-binding protein and phosphorylation of MARCKS could affect actin dynamics and thereby modulate melanoma cell motility and/or invasion, we further studied the molecular and subcellular events during WNT5A-mediated MARCKS phosphorylation in melanoma cells." (PMID 32033033, 2020). "Interestingly, our quantitative results further revealed that the fluorescence intensity of phosphorylated MARCKS was significantly higher at the cell periphery and at the leading edge of A2058 melanoma cells exposed to rWNT5A compared to the vehicle (control)-treated cells." (PMID 32033033, 2020). "Another alternative downstream target of WNT5A-induced PKC signaling in melanoma cells that so far has only been used to monitor PKC activity in these cells is the phosphorylation of the endogenous PKC substrate myristoylated alanine-rich C-kinase substrate (MARCKS)." (PMID 32033033, 2020).
melanoma (continued). "Based on a previous finding that the MARCKS protein has been implicated in the formation of such structures and our present results, we speculated that WNT5A signaling could promote melanoma cell migration and invasion via translocation of phosphorylated MARCKS to the leading edge of melanoma cells." (PMID 32033033, 2020). "Most interestingly, the ability of WNT5A to stimulate the invasiveness of MARCKS siRNA-silenced melanoma cells was completely abolished, suggesting an essential WNT5A-downstream signaling role of MARCKS in its ability to induce melanoma cell invasion." (PMID 32033033, 2020). "We silenced WNT5A in HTB63 melanoma cells with two different WNT5A siRNAs and observed that there was only a minor effect on the total MARCKS level." (PMID 32033033, 2020). "Based on these results, we decided to focus on the Ser-159/163 phosphorylation of the MARCKS protein and how it relates to WNT5A signaling and melanoma cell invasion." (PMID 32033033, 2020). "Interestingly, the combined inhibition of PKC and ROCK signaling caused more than 90% inhibition of MARCKS phosphorylation in both A2058 and A375 melanoma cell lines, and this inhibition could not be rescued by cotreatment with rWNT5A." (PMID 32033033, 2020). "Interestingly, our results revealed a weak positive correlation between MARCKS and WNT5A mRNA expression in melanoma patient tissue." (PMID 32033033, 2020). "Since MARCKS phosphorylation hinders its actin cross-linking ability, we wanted to study the consequence(s) of WNT5A-mediated MARCKS phosphorylation for the F-actin network of melanoma cells." (PMID 32033033, 2020). "Interestingly, the Ser-159/163 phosphorylation of MARCKS was significantly decreased after WNT5A knockdown in HTB63 melanoma cells." (PMID 32033033, 2020). "However, to gain further insight into the cellular mechanisms behind the observation that MARCKS expression could predict the prognosis of melanoma patients, we used the HOPP melanoma cell line database and analyzed the association of MARCKS expression with melanoma cell proliferation and invasion." (PMID 32033033, 2020). "WNT5A is a well-known mediator of melanoma cell invasion and metastasis via its ability to activate protein kinase C (PKC), which is monitored by phosphorylation of the endogenous PKC substrate myristoylated alanine-rich c-kinase substrate (MARCKS)." (PMID 32033033, 2020). "Interestingly, the database findings on MARCKS are very similar to those of the WNT5A ligand, which is well known for its ability to promote melanoma invasion and metastasis and has been shown to activate PKC." (PMID 32033033, 2020). "Other newly identified targets of miR‐21, including Maspin, MARCKS, and RECK, have been shown to participate in decreasing cancer cell invasion through matrigel and therefore warrant exploration into their ability to do so in melanoma." (PMID 25587717, 2015). "Moreover, MANS peptide is able to suppress WNT5A-induced melanoma cell invasion in vitro by inhibiting MARCKS phosphorylation without affecting MARCKS expression." (PMID 36230850, 2022). "However, a possible direct contribution of MARCKS in WNT5A-mediated melanoma cell invasion has not been investigated." (PMID 32033033, 2020). "Here, A2058 and A375 melanoma cells were exposed to 0.2 μg/mL recombinant WNT5A (rWNT5A) protein for different time periods (starting at 15 minutes to a maximum of 24 hr) to observe any changes in total expression and Ser-159/163 phosphorylation levels of MARCKS." (PMID 32033033, 2020). "However, a possible functional role of the MARCKS protein in WNT5A-induced melanoma cell migration and invasion has not yet been studied." (PMID 32033033, 2020). "Since MARCKS phosphorylation is important for the control of actin dynamics, our novel observations of PKC and RhoA-ROCK signaling being involved in melanoma cell invasion mediated by WNT5A-induced MARCKS phosphorylation, suggest the importance of these signaling pathways in melanoma." (PMID 32033033, 2020).
melanoma (continued). "Interestingly, however, we observed that rWNT5A exposure could not rescue the anti-invasive effect of MARCKS siRNA silencing in A2058 melanoma cells." (PMID 32033033, 2020). "Although WNT5A/PKC signaling has been previously reported to promote melanoma cell migration and invasion resulting in increased metastasis, a functional role of the PKC substrate MARCKS has not been studied." (PMID 32033033, 2020). "Next, we employed a peptide inhibitor of MARCKS phosphorylation that did not affect MARCKS expression and found that it abolished WNT5A-induced melanoma cell invasion." (PMID 32033033, 2020). "The results revealed that all four melanoma cell lines (WM852, HTB63, A375 and A2058) used in our study expressed significant levels of MARCKS irrespective of their WNT5A levels." (PMID 32033033, 2020).
prostate carcinoma (11 papers, 2012 to 2025). A carcinoma that arises from epithelial cells of the prostate gland. "MARCKS, a substrate of protein kinase C, is implicated in cytoskeletal movement processes and has been linked to apoptosis in prostate cancer cells." (PMID 39376659, 2024). "Consistent with this, we have demonstrated an association of MARCKS with BCR in prostate cancer clinical samples." (PMID 29069765, 2017). "In prostate cancer, the MARCKS down-regulating microRNA-21 (miR-21) is overexpressed, and selective miR-21 suppression results in apoptosis sensitivity, and cell invasion inhibition." (PMID 31058089, 2019). "Knockdown of MARCKS reduced migration and invasion of prostate cancer cells, reduced MMP9 mRNA expression, as well as decreasing cell spreading and increased cell:cell adhesion in prostate cancer cell colonies." (PMID 29069765, 2017). "In this study we have characterised a functional role for MARCKS in prostate cancer by investigating its role in proliferation, viability, apoptosis, migration and invasion." (PMID 29069765, 2017). "Here, we have demonstrated that knockdown of MARCKS alters actin arrangement in prostate cancer cells." (PMID 29069765, 2017). "Prostate cancer cell lines were transfected with siRNA targeting MARCKS or a control and functional endpoints of migration, invasion, proliferation, viability and apoptosis were measured." (PMID 29069765, 2017). "The advantageous expression of MARCKS in cancer stroma was further confirmed in another two stoma profiling datasets of lung and prostate cancer and in tumor stroma of EOC patient samples." (PMID 27081703, 2016). "Down-regulation of MARCKS by siRNA was able to increase the invasiveness of DU-145 prostate cancer cells." (PMID 23272133, 2012). "Studies using prostate cancer cells have shown that miR-21 targets myristoylated alanine rich protein kinase c substrate (MARCKS), which is involved in cellular processes, such as cell adhesion and cell motility through regulation of the actin cytoskeleton." (PMID 22408395, 2012). "Interestingly, MARCKS inhibition was reported to reduce the migration and invasion of prostate cancer cells." (PMID 40429857, 2025). "Moreover, recent studies using prostate cancer cells showed that miR-21 promotes cell invasion by directly targeting MARCKS." (PMID 31807240, 2019). "Interestingly, pomegranate decreased the expression of miR-21 and increased MARCKS in prostate cancer cells." (PMID 31807240, 2019). "In summary, our results show a role for MARCKS in promoting invasion in prostate cancer." (PMID 29069765, 2017). "The role of MARCKS in prostate cancer has not previously been studied but has been associated with metastasis and disease progression in lung and colon cancer." (PMID 29069765, 2017). "Using siRNA-mediated knockdown of MARCKS, prostate cancer cell lines showed reduced invasion." (PMID 29069765, 2017). "Thus, in prostate cancer, MARCKS promotes invasion through its regulation of the cytoskeleton." (PMID 29069765, 2017). "The characterisation of the role of MARCKS in prostate cancer, as outlined here, provides a basis for future studies to elucidate the precise mechanism behind MARCKS-induced invasion and whether its inhibition can be used therapeutically to prevent prostate cancer disease progression." (PMID 29069765, 2017). "The results of this study have identified for the first time an increased expression of MARCKS protein in clinical samples of prostate cancer from BCR patients compared to non-BCR patients." (PMID 29069765, 2017). "PC3 is tumorigenic in mice whereas PNT2 is non-tumorigenic in nude mice Knockdown of MARCKS did not have any effect on cellular proliferation of prostate cancer cell lines." (PMID 29069765, 2017). "We provide evidence that MARCKS promotes migration and invasion in prostate cancer cells and that this transfers clinically, as MARCKS is upregulated in BCR compared to non-BCR men with prostate cancer." (PMID 29069765, 2017).
prostate carcinoma (continued). "The promotion of invasion by MARCKS does not appear to be mediated by EMT in prostate cancer." (PMID 29069765, 2017).
glioblastoma (8 papers, 2012 to 2023). The most malignant astrocytic tumor (WHO grade IV). "In glioblastoma multiforme (GBM) model systems, knockdown of MARCKS is associated with increased resistance to radiation by increasing DNA repair in PTEN-null GBM cells in vitro and orthotopic xenografts in vivo." (PMID 36230850, 2022). "Meanwhile, MARCKS is a prognosis reporter for glioblastoma and contributes to the intracranial tumor proliferation rate." (PMID 30322114, 2018). "Studies have proved that the effector domain of MARCKS can be recognized as a nuclear localization signal which enables MARCKS to enter the nucleus in glioblastoma cells." (PMID 29757215, 2018). "Overexpression of MARCKS has been found in various cancers including hepatocellular carcinoma, pancreatic cancer, glioblastoma and cholangiocarcinoma." (PMID 22745766, 2012). "In glioblastoma multiforme (GBM), down-regulation of MARCKS expression with small interfering RNA in cells constitutively expressing EGFRvIII, a mediator of MARCKS phosphorylation, leads to decreased cell adhesion, spreading, and invasion in vitro." (PMID 36230850, 2022). "Therefore, as a malignant tumor subtype glioblastoma, the expression of MARCKS may be a potential biomarker for the identification of glioblastoma." (PMID 30322114, 2018). "We have confirmed that MARCKS is indeed present in the nucleus in Glioblastoma multiforme (GBM) cells." (PMID 26470026, 2015). "Moreover, MARCKS plays a critical role in EGFR-induced invasion of glioblastoma cells." (PMID 22745766, 2012). "As Markov blanket genes, DUSP1 was common in Pilocytic and Diffuse tumors; EIF4A1 was common in Pilocytic, Diffuse and Anaplastic tumors; MARCKs was common in Diffuse and Anaplastic tumors and SERBP common in Anaplastic and Glioblastoma tumors." (PMID 23737970, 2013). "Rule 11 involves four functional genes, indicating that high expression of HSPA1B and MARCKS, together with the low expression of RPSAP58 and PRDX1, may indicate that a patient may suffer from glioblastoma." (PMID 30322114, 2018).
colorectal cancer (7 papers, 2017 to 2024). A primary or metastatic malignant neoplasm that affects the colon or rectum. "For instance, in colorectal cancers, MARCKS is a preferential target of mutational inactivation in tumors, which is associated with an adverse prognosis." (PMID 31058089, 2019). "However, the inactivation of MARCKS is commonly observed in human colon cancers and associated with adverse patient outcomes, suggesting that MARCKS acts as a suppressor of progression in human colorectal cancer." (PMID 36230850, 2022). "MARCKS was found to have an important role in the progression of colorectal cancer and to be implicated in cell motility, invasion and proliferation of colon cancer cells, whereas its inhibition clearly affected these cancer features and reduced the metastatic events." (PMID 29295532, 2017). "Although the role of MARCKS in the development of cancers remains a topic of debate, it may suppress cell growth in colorectal cancer." (PMID 39252972, 2024). "Of note, lack of MARCKS expression in colorectal cancer (CRC) has been associated with a more aggressive tumor phenotype and unfavorable prognosis, suggesting a tumor suppressor function of MARCKS." (PMID 32056006, 2020).
multiple myeloma (7 papers, 2013 to 2021). "Results from our lab demonstrated that low levels of miR-34a are associated with an increased expression of MARCKS, higher resistance to anti-myeloma drugs, disease progression, and an overall poor prognosis in MM." (PMID 33958003, 2021). "Research from our lab investigating the role of MARCKS in hematological malignancies provided the earliest evidence of its involvement in drug-resistant multiple myeloma (MM), chiefly against the proteasomal inhibitor bortezomib." (PMID 33958003, 2021). "MARCKS is a substrate of protein kinase C (PKC), and it has previously reported that inhibition of MARCKS overcome the drug resistance in multiple myeloma cells." (PMID 33578797, 2021). "There are elevated levels of phosphorylated MARCKS in highly invasive non-small-cell lung cancer cells, in drug-resistant myeloma, or in kidney cancer cells." (PMID 31058089, 2019). "Inhibition of MARCKS activity by a PKC inhibitor enzastaurin or siRNA-mediated knockdown significantly enhanced the sensitivity of resistant myeloma cell lines and primary myeloma samples to therapy." (PMID 28265552, 2017). "They showed that MARCKS inhibition combined with bortezomib treatment could overcome bortezomib resistance and effectively inhibit tumor growth in a multiple myeloma xenograft model." (PMID 28265552, 2017). "Therefore, combination of a MARCKS and a proteaseome inhibitor could represent a basis to develop novel myeloma therapies." (PMID 31058089, 2019). "Another strategy to inhibit MARCKS phosphorylation is the application of the macrocyclic bisindolylmaleimide Enzastaurin, a PKC inhibitor significantly enhancing the sensitivity of drug-resistant cells toward the proteasome inhibitor bortezomib and other anti-myeloma drugs." (PMID 31058089, 2019).